CFL1 (cofilin 1)
Diseases named in the same sentence as CFL1 in open-access papers (continued):
Sharing a sentence is not in itself a finding about the gene and the disease.
rectum adenocarcinoma (1 paper, 2021). An adenocarcinoma arising from the rectum. "In according, we found increased methylation level of the CFL-1 and SSH1 promoter regions in colon and rectum adenocarcinoma tissues from the TCGA database, suggesting that differences in the expression of CFL-1 and SSH1 in CRC may be related to epigenetic modifications." (PMID 33482809, 2021).
rhabdomyosarcoma (1 paper, 2020). A rare aggressive malignant mesenchymal neoplasm arising from skeletal muscle. "This protein is upregulated in the presence of the enterovirus 71 in rhabdomyosarcoma, and the hyperphosphorylation of serine 7 was detected in various types of cancer, suggesting that Cofilin 1 has a role in cancer development." (PMID 32337254, 2020).
squamous cell carcinoma (1 paper, 2018). A carcinoma arising from squamous epithelial cells. "Smoker patients with squamous cell carcinoma, lymph node metastasisand sputum CFL1>1.475 pg/mL showed augmented chance of death, suggesting lungcancer aggressiveness." (PMID 29846436, 2018).
Stroke (1 paper, 2025). Sudden impairment of blood flow to a part of the brain due to occlusion or rupture of an artery to the brain. "Here, cofilactin rod formation and oxidative stress were evident as early as 6 h after stroke, with cofilactin rods identified as rod-like accumulations of cofilin-1, and oxidative stress indicated by nuclear DNA damage." (PMID 41152941, 2025).
tongue tumor (1 paper, 2018). "The present study identified cofilins (CFL1 and CFL2) and tropomyosin family proteins (TPM3 and TPM4) are significantly upregulated, in contrast, myosin family proteins (MYL2, MYL4 and MYLPF) were downregulated in tongue tumor samples as compared to normal samples." (PMID 29371635, 2018).
vulvar tumor (1 paper, 2017). "In vulvar tumor, CFL1 has been reported to have an effect on carcinogenesis and progression." (PMID 28903403, 2017).
tumor (79 papers, 2008 to 2025). "Cofilin 1(CFL1) is upregulated in the tumor tissues of HCC and is significantly associated with the overall survival and disease-free survival of HCC patients." (PMID 40051627, 2025). "Higher cofilin-1 concentrations were associated with advanced tumour stage, poor disease free survival and poor overall survival." (PMID 34678587, 2022). "(AUC = 0.838, 95% confidence interval = 0.773–0.876) Furthermore, higher serum CCT8 and CFL1 concentrations were significantly associated with the presence of vascular invasion, advanced tumor stage, poor disease-free survival, and poor overall survival." (PMID 34359304, 2021). "For example, in addition to their well characterised roles in actin cytoskeleton dynamics, cofilin-1, fibronectin and fibulin-1 have also been implicated in cellular migration, tumour invasion and mitosis." (PMID 34832109, 2021). "To further analyze the association between the data of CFL-1 obtained by IHC score with clinicopathological parameters, we separate tumor samples into high or low expression groups according to the median value obtained in the IHC score." (PMID 33482809, 2021). "CFL1 expression is critically associated with cell migration and tumor invasion, and can be a marker of tumor progression." (PMID 28903403, 2017). "Other downregulated genes included fatty acid binding protein 7 (FABP7), previously linked to the proliferation, migration, and invasion of tumor cells, and cofilin 1 (CFL1), a central regulator protein of actin dynamics in migrating cells." (PMID 26918341, 2016). "The increased level of actin and decreased level of cofilin-1 in the supernatant from the irradiated tumor cells appear to be associated with rearrangement of cellular cytoskeleton after a high dose of radiation." (PMID 27561007, 2016). "Interestingly, the expression of LIMK1 and its substrate, Cofilin-1, in OS is associated with clinical stage, distant metastasis, and tumour grade." (PMID 34944050, 2021). "CFL1 presented diagnostic value in detecting lung cancerand was associated to tumor aggressiveness." (PMID 29846436, 2018). "Many authors have considered Cfl-1 protein as a diagnostic/prognostic tumor biomarker." (PMID 28025492, 2016). "Restoring tumor-suppressive miRNAs like miR-145 and miR-138 or blocking oncogenic miRNAs like miR-21 can alter actin-binding proteins like cofilin 1 and ezrin, which will alter cytoskeletal dynamics and lessen invasiveness." (PMID 40723199, 2025). "Cofilin-1 promotes tumor cell spread by weakening cell connections, enabling them to break away from the primary tumor." (PMID 40297849, 2025). "CFL1 is also highly expressed in tumor tissues of HCC patients who are insensitive to sorafenib and is associated with poor prognosis." (PMID 40051627, 2025). "Cofilin-1 (CFL1) is crucial for processes like tumor progression, cell motility, adhesion, invasion, and angiogenesis." (PMID 40072086, 2025). "MiR-145 exhibits tumor-suppressive effects by targeting cofilin-1, a vital protein involved in actin filament depolymerization." (PMID 40723199, 2025). "In the context of TNBC, the overexpression of Cofilin-1 assumes a critical function in facilitating tumor infiltration and metastatic dissemination." (PMID 40297849, 2025). "Enhanced filopodium formation and cell migration capabilities in cofilin-overexpressing PCa cells further underscore the pivotal involvement of cofilin-1 in tumor progression." (PMID 39055653, 2024). "Subsequent to treatment with thapsigargin, there is a notable rise in cofilin-1 protein expression in PCa cells, hindering tumor growth by modulation of the F-actin/cofilin-1/paxillin pathway and the Akt-mTOR pathway." (PMID 39055653, 2024). "In comparison, the tumor size increases by more than six fold for the mice treated with free sorafenib, NPs(siCTL/Sor) or NPs(CFL1)." (PMID 37203277, 2023).
tumor (continued). "Despite several reports evidencing an opposing effect of CFL1 overexpression in tumor tissues, many authors maintain that this protein has more potential as a prognostic marker for tumor recurrence." (PMID 37226274, 2022). "CFL1 is considered as a biomarker of tumor cell migration and invasion in many tumor diseases, and is proposed as a target for antitumor therapy." (PMID 37226274, 2022). "The tumor size (T1–4) was positively correlated with the number of CFL1+CD326+ CTCs, and the type of epithelium was correlated with the number of CAP1+CD326+ CTCs." (PMID 37226274, 2022). "In sum, our research suggests the existence of a regulatory mechanism that can be summed up as follows: “Ionizing Radiation → LncRNA CRYBG3 → ADF/CFL1 --- |F-actin --- | LATS1/2 --- | YAP/TAZ → tumor proliferation, migration and invasion”." (PMID 35246511, 2022). "Cofilin-1 regulates tumor cells metastasis; in particular, the overexpression of cofilin-1 increases the speed of tumor migration." (PMID 35887090, 2022). "Many studies on the role of the actin cytoskeleton in tumor progression have focused on ABPs, specifically cofilin-1 (CFL1) and profilin-1 (PFN1)." (PMID 37226274, 2022). "The resulting elevation in ROCK1 expression drives LIMK1/Cofilin-1 signaling that promotes pro-tumor cellular behaviors." (PMID 33414429, 2021). "In recent years, many studies have found that CFL1 plays an important role in movement of tumor cells, the regulation of adhesion between tumor cells and extracellular matrix, the mitosis of tumor cells, and the speed and depth of tumor cell invasion." (PMID 33791303, 2021). "In order to illustrate the molecular mechanism of NJXA on tumor metastasis, the protein expression levels of CFL1, F-actin and G-actin were examined in tumor tissues by immunohistochemical analysis." (PMID 33791303, 2021). "CFL1 knockdown remarkably reduced the volume and weight of tumours formed by HCCLM3 cells (p < 0.05)." (PMID 33784016, 2021). "The results showed that the mRNA level of CFL1 was significantly increased in tumor tissues as compared with tumor free tissues." (PMID 33791303, 2021). "What is more, multivariate analysis showed that only tumour size, tumour number, venous infiltration, and CFL1 level are independent prognostic indicators of OS in HCC." (PMID 33784016, 2021). "In vitro and in vivo, experiments that were performed recognized CFL1 as a driver of tumour growth and metastasis in HCC." (PMID 33784016, 2021). "Western blotting and IHC analysis consistently indicated a gradually upregulated expression of CFL1 in tumour‐adjacent, HCC, and PVTT tissues." (PMID 33784016, 2021). "The results further demonstrated that CFL1 expression in HCC was significantly higher than that in tumour‐adjacent tissues." (PMID 33784016, 2021). "Previous studies demonstrated that changes in cofilin-1 or p-cofilin-1 patterns played an important role in multidrug resistance in tumor cells." (PMID 33644057, 2021). "It was found that CFL1, N‐cadherin, and vimentin levels were reduced while E‐cadherin expression was increased in tumour tissues (CFL1 knockdown group) than in those from controlled tissues." (PMID 33784016, 2021). "Reinforcing this suggestion, it was reported that LIMK1 is crucial for invasiveness and metastatic activity, and regulating the phosphorylation of CFL-1 during mitosis contributes to appropriate cytokinesis, proliferation, and extension of the tumor." (PMID 33482809, 2021). "MCL1 has also been shown to promote tumor invasiveness via interaction with Cofilin 1, a cytoskeletal remodeling protein, and phosphorylated SRC." (PMID 34469478, 2021). "Compared to tumour‐adjacent liver tissues, CFL1 expression was prominently increased in HCC tissues, especially was higher in PVTT." (PMID 33784016, 2021). "Some studies have shown that the activation of CFL1 is closely related to the malignant invasive properties of tumor cells." (PMID 33791303, 2021).
tumor (continued). "One of the SEMA7A receptors is PlexinC1, a transmembrane protein that can act as a tumor suppressor through the inhibition of cofilin 1 (CFL1), an actin-binding protein that play role in cell migration." (PMID 35008571, 2021). "In various cancer types, including gastric, prostate, urothelial, breast, and vulvar, elevated expression of CFL-1 and its regulators, LIMK1/SSH1, have been implicated in tumor progression and aggressiveness, as well as in poor survival rate." (PMID 33482809, 2021). "The elevated expression of CFL1 was associated with unfavourable characteristics of HCC, including HBV infection, tumour diameter ≥5 cm, multiple tumours, venous infiltration, and advanced TNM stage." (PMID 33784016, 2021). "Subcutaneous tumour tissues from the CFL1 knockdown group showed less PLD1 staining than those from the control group." (PMID 33784016, 2021). "CFL1 is also recognized as a tumour‐promoting factor in Ewing's sarcoma family tumours (ESFTs) cell proliferation and metastasis." (PMID 33784016, 2021). "In summary, our study demonstrated that high expression of CFL1 is closely related to tumor metastasis and poor clinical outcomes in human HCC." (PMID 33791303, 2021). "Many studies demonstrated that high-expression levels of cofilin-1 in many cancers correlated with tumor metastasis, chemotherapy resistance, and poor prognosis." (PMID 33644057, 2021). "Further, 100 pairs of collected HCC and non‐tumour tissues were subjected to RT‐qPCR and immunoblotting for CFL1 expression." (PMID 33784016, 2021). "Based on our results, the expression of CFL1 was down regulated and this correlates with tumor metastasis in HCC patients." (PMID 33791303, 2021). "Since enhanced cell survival, metastasis and invasion extensively exist in tumor cell, activity of Cofilin 1, affected by expression level, phosphorylation level, pH and subcellular localization, closely correlates with tumorigenesis and tumor development." (PMID 30858759, 2019). "In cancer cells, Cofilin 1 activity, which is affected by factors of phosphorylation level, pH, subcellular localization and binding of phosphoinositides, is necessary for tumor cell motility and invasion." (PMID 30858759, 2019). "Here, we found another regulated pathway by miR-182-5p that can elevate levels of Cofilin 1 in tumor cells." (PMID 30858759, 2019). "The results showed that xenograft tumor volume and growth of miR-182-5p inhibitor and Cofilin 1 groups were obviously increased compared with control (RT4, p < 0.05)." (PMID 30858759, 2019). "LIMK1 has only one known physiological substrate: CFL1, a small protein that is required for tumor cell movement." (PMID 30873211, 2019). "The expression levels of AXL, GAS6, Claudin-1, and Cofilin-1 genes were investigated in a fresh, frozen tumor sample and normal adjacent tissue by real-time PCR (RT-PCR)." (PMID 31700829, 2019). "In our study, we found that expression of Cofilin 1 accelerates tumor cell proliferation and decreases cells of G1-arrested." (PMID 30858759, 2019). "Then, cell experiments were performed to analysis the effect of miR-182-5p/Cofilin 1 pathway on tumor cell proliferation, migration, invasion and colony forming efficiency." (PMID 30858759, 2019). "The ROCK/PTEN signaling pathway plays an important role in tumor cells apoptosis via mitochondrial translocation of cofilin-1." (PMID 30622602, 2018). "CFL1 expression affects the tumor cell migration induced by growth factors and increases the migration speed of the tumor cells." (PMID 29347944, 2018). "As a type 1 member, CFL1 is an important factor involved in the regulation of tumor cell metastasis and invasion and is closely related to the pathological processes of tumors." (PMID 29347944, 2018). "Consistent with the results obtained above, the expression of CFL1 was markedly higher in tumor tissues than in matched adjacent normal tissues." (PMID 28388575, 2017).
tumor (continued). "Cofilin 1 (CFL1) is an important regulatory factor of cytoskeletal reorganization in tumor cells, and its expression strongly correlates with the EMT of tumors." (PMID 28388575, 2017). "Tumor volumes were higher in mice injected with T24 or RT4 cells overexpressing Cofilin 1 than in the control group (NC group)." (PMID 29190896, 2017). "CFL1 has been suggested to block tumor cell apoptosis, which is beneficial to tumor cell growth and decreases tumor cell radiosensibility." (PMID 28903403, 2017). "A previous study demonstrated that Cofilin 1 can transport G-actin and other proteins to the nucleus, which results in changes in gene expression that increase tumor cell proliferation and viability." (PMID 29190896, 2017). "Previous studies demonstrated that changes in cofilin-1 or p-cofilin-1 patterns played an important role in multidrug resistance in tumour cells." (PMID 27872653, 2016). "Cofilin-1 is a key factor in tumor cell migration and metastasis, being overexpressed in a wide variety of cancers." (PMID 27206672, 2016). "Accordingly, it is possible to think that Cfl-1 is a common participant in various tumor phenotypes." (PMID 28025492, 2016). "Over the last 20 years, several studies have pointed cofilin-1 as an important protein in aggressive cancer cell behavior, due to its involvement in the coordination of tumor cell migration and invasion." (PMID 25784483, 2015). "At the same time, NAV2 activated the SSH1L/cofilin-1 pathway and facilitated tumor cell migration and invasion through F-actin polymerization." (PMID 26452645, 2015). "Although mammals have several cofilin isoforms, cofilin 1 (referred to here as cofilin) is the most abundant isoform in most of the cultured mammalian cell lines and in tumor cell lines." (PMID 25593987, 2014). "Our results showed total cofilin-1 predominantly localized in the cytoplasm and p-cofilin in the cytoplasm and nuclei of tumor cells." (PMID 23227181, 2012). "The in vivo antitumor effects of cofilin-1-ShRNA complexed with cationic liposome (DOTAP/Chol) were evaluated in terms of pulmonary metastatic tumor growth and survival in mice." (PMID 22087286, 2011). "PKM2 was up-regulated 2.9-fold and cofilin-1 was up-regulated 3.7-fold in tumor compared to paired surrounding normal tissue (p<0.05)." (PMID 22087286, 2011). "Similarly, in LUSC, it was shown that CFL1 mRNA expression increased with tumor growth, while the protein level of cofilin translated from CFL1 diminished, suggesting a posttranslational regulatory mechanism." (PMID 39201394, 2024). "K-M curves showed that upregulated TRNP1, CCDC112, CFL1 were associated with poor OS) and CYB5D2, SLC22A1 were protective genes (expression of CYB5D2, SLC22A1 were decreased in tumor tissues, and higher expression of CYB5D2, SLC22A1 was associated with good OS)." (PMID 36881382, 2023). "Levels of CFL-1 depend on the cancer cell, tumor type, and extent of proliferation and migration." (PMID 37174083, 2023). "Besides analyzing the public database, we also used immunohistochemistry (IHC) to examine CFL1 expression in the surgically resected tumor samples of HCC patients (n = 120)." (PMID 37203277, 2023). "By comparing the transcriptome sequencing data of sorafenib‐sensitive and ‐insensitive HCC patients, it is revealed that cofilin 1 (CFL1) is highly expressed in the tumor tissues of sorafenib‐insensitive HCC patients and closely correlated with their poor prognosis." (PMID 37203277, 2023). "It was also reported that the DRD2 agonists could exert anti-tumor effects through ROCK-mediated inactivation of Cofilin-1 or inhibiting EGFR/AKT/MMP-13 pathway." (PMID 35463319, 2022). "However, specific molecular mechanisms requiring CFL1 involvement in the formation of malignant phenotypes of tumor cells are yet to be described." (PMID 37226274, 2022).